CD28 (CD28 molecule)
Diseases named in the same sentence as CD28 in open-access papers (continued):
Sharing a sentence is not in itself a finding about the gene and the disease.
myeloma (continued). "In addition, screening of multiple myeloma surface antigens has identified other promising targets, including CD28 (Tp44), CD48 (BLAST), CD74 (CLIP), CD138 (SDC1), CD229 (SLAMF3), CD319 (SLAMF7), CCR10 (GPR2), TAC1 (NPK), TXNDC11, SLC1A5 (AAAT)." (PMID 41369346, 2025). "CD28 is not only expressed by T lymphocyte but also by myeloma cells." (PMID 40013150, 2025). "Surprisingly, they found that CD86 is often co‐expressed with CD28 on myeloma cells." (PMID 40635602, 2025). "As CD28 expression has been found on multiple myeloma cells, we examined whether the percent of multiple myeloma cells positive for CD28 affected response to SAR4422257." (PMID 38421887, 2024). "Importantly, our study quantified the expression of CD28 on myeloma cell lines and patient samples, including newly diagnosed and relapsed/refractory cases." (PMID 38786100, 2024). "Also, a phase II study of targeting CD28 in multiple myeloma with abatacept (CTLA4-Ig) determine the therapeutic efficacy to overcome resistance to chemotherapy (NCT03457142)." (PMID 37122695, 2023). "This study showed that CS1-CAR NK-92 cells (2nd generation CAR, CD28) could effectively inhibit tumor growth in the multiple myeloma (MM) xenograft mouse models." (PMID 36032149, 2022). "Moreover, abnormal CD28 progression on myeloma cells correlates with metastasis, suggesting that IL-8 plays a role in promoting myeloma metastasis." (PMID 33808304, 2021). "Since we have shown that CD28 itself is important in myeloma progression and survival, this CD28/CD86 axis may represent a possible mechanism by which cis-interactions in the myeloma cell microenvironment may facilitate survival and disease progression." (PMID 32751699, 2020). "Also, CD28 co-expression in T-cells collected from untreated myeloma patients was shown lower in comparison to T-lymphocytes from healthy individuals (right)." (PMID 33363008, 2020). "The antibody was even more effective at driving T cell cytotoxicity when myeloma cells expressed CD28, and it could potentially be used for the treatment of myeloma patients." (PMID 32326073, 2020). "Furthermore, blocking CD28 inhibited chemotherapy-induced cell apoptosis, and the CD28 signaling pathway was associated with the downstream activation of PI3K/Akt and inactivation of the FoxO1 in multiple myeloma." (PMID 31565151, 2019). "Similar to T cells, CD28 activation in multiple myeloma cells activated PI3K/Akt signaling, which might regulate the apoptotic resistance of multiple myeloma." (PMID 31565151, 2019). "Therefore, we assessed surface expression of PD-1, CTLA-4, CD160, and 2B4, as well as expression of CD57 and CD28 in myeloma CD8+ T cells before and after therapy with immunomodulatory drugs and dexamethasone." (PMID 27809856, 2016). "Notably, the percentage of senescent CD57+CD28− CD8+ T cells was significantly lower in treated myeloma patients when compared to untreated patients." (PMID 27809856, 2016). "The CD8+CD57+CD28− phenotype may represent cytotoxic T cells in myeloma which are terminally differentiated, i.e., senescent." (PMID 27809856, 2016). "Here, we assessed the expression of inhibitory molecules PD-1, CTLA-4, 2B4, CD160, senescence marker CD57, and CD28 on T cells of naive and treated myeloma patients in the bone marrow and peripheral blood and collected data on T cell subset distribution in both compartments." (PMID 27809856, 2016). "This suggests that CD28 may be a promising target for the treatment of advanced myeloma." (PMID 38786100, 2024). "In addition, activation of CD28 also induces activation of PI3 kinase signaling in MM PC, with downstream nuclear factor kappa B (NFkB) activation causing a pro-survival effect, which further strengthens the role of CD28 in the stroma–myeloma cell interaction." (PMID 35407416, 2022).
myeloma (continued). "tTReg cells were stimulated using CD3/CD28-coated beads for 5 days, determining their proliferative response by tritiated thymidine incorporation, comparing their response to sorted nTReg cells from healthy donors and patients with myeloma, similarly stimulated." (PMID 22666318, 2012). "The conclusion is that the trispecific SAR442257 operates via dual targeting of CD38 and CD28 on myeloma cells and of CD3 and CD28 on T lymphocytes, showing superior MM killing compared to bispecific antibodies." (PMID 40013150, 2025). "Myeloma cells expressing CD86 and CD28 can likely activate each other, promoting their survival and reducing their dependence on the microenvironment." (PMID 40635602, 2025). "It simultaneously targets CD3, CD28, and CD38, leading to sustained T-cell activation and specific targeting of myeloma cells." (PMID 39990653, 2025). "In our study, with the blockade of CD28, the entry of MYXV into myeloma cells was decreased in two of the four patients and increased in one." (PMID 38251379, 2024). "In particular, high expression levels of CD28 and CD86 have been identified as poor prognostic markers in myeloma patients, indicating their crucial role in disease survival and progression mechanisms." (PMID 38831187, 2024). "Cell identity was validated using human antibodies and probes consistent with a myeloma origin for example, CD45dim/CD38+/CD56+/CD19‐/CD28+/CD138+or−/cLambda+/cKaappa−." (PMID 35789025, 2022). "Comparison of myeloma cells to the two B-lymphoblastoid cell lines also showed CD138/SDC1 and CD28 as characterizing myeloma cells, while CD19, CD22, and CD20 characterized late-stage B-cells." (PMID 35840578, 2022). "Knockout of CD28 leads to decreased antibody titers of long-lived plasma cells in mice, and knockdown of CD28 or CD86 with short hairpin RNA leads to myeloma cell death in HMCL." (PMID 33634031, 2020). "We here see a similar situation in myeloma bone marrow, i.e., a high proportion of CD8+ T cells which lost CD28 expression and concomitantly gained CTLA-4 expression and upregulated 2B4." (PMID 27809856, 2016). "We used the same assay to assess whether CD28 engagement influences levels of miR29b and its target DNMT3B in U266 and RPMI 8226 myeloma cells." (PMID 38654298, 2024). "Both CD28 and CD86 are essential for PCs development, myeloma survival and therapy resistance." (PMID 35692781, 2022). "Our panel incorporated antigens rarely included in myeloma MRD panels, like CD200 and CD28." (PMID 34485145, 2021). "It is likely that the molecule in the first clinical trial to test this technology will have specificities for CD38, CD3 and CD28, with the goal of simultaneously enhanced T cell activation through CD3 and CD28 and direct targeting of myeloma cells through CD28 and CD385." (PMID 32620755, 2020). "We analyzed in vitro the antigen-specific T-cell responses of healthy donors and patients with multiple myeloma with or without the addition of autologous CD8+CD28− T-cells in the absence and presence of lenalidomide." (PMID 29228683, 2017). "In both healthy and diseased samples, most T cells lacked CD28 expression whereas CD57 expression was significantly increased in myeloma bone marrow T cells." (PMID 27809856, 2016). "In addition to the activity on myeloma plasma cells, T cells may be engaged through all three targets, CD3, CD28, and CD38." (PMID 38786100, 2024). "To determine whether the regulation of miR29b and DNMT3B levels by CD28 involved activation of the PI3K/AKT pathway, we simultaneously exposed U266 and RPMI 8226 myeloma cells to CD28 stimulation and PI3K inhibition with the PI3K inhibitors LY294002 and buparlisib." (PMID 38654298, 2024). "In untreated myeloma patients, a slight increase of CD27−/28− T-cells to a mean fraction of 13.6% (± 4.13) and decrease of CD27+/CD28+ T-cells to a mean fraction of 75.2% (± 4.53) in comparison to healthy donors could be demonstrated (p=0.02 and p=0.013, respectively)." (PMID 33363008, 2020).
viral infection (46 papers, 2006 to 2025). "CD4+ T cells were isolated from peripheral blood mononuclear cells (PBMCs) using immunomagnetic purification and activated via CD3/CD28 co-stimulation to maximize their susceptibility to viral infection." (PMID 39205294, 2024). "Here, we demonstrated that the defective development of memory CD8+ T cells in Cd28−/− or Ox40−/− mice was caused by the reduced expression of two transcriptional factors c-Myc and Nfkb1 during viral infection." (PMID 26791245, 2016). "The life-long homeostasis of memory CD8+ T cells as well as persistent viral infections have been shown to facilitate the accumulation of highly differentiated CD8+CD28− T cells, a phenomenon that has been associated with an impaired immune function in humans." (PMID 22435726, 2012). "Furthermore, several pathologic conditions such as viral infections are also known to cause CD28 downregulation." (PMID 38993862, 2023). "Indeed, impaired T-cell function predisposes to viral infections, and poor CD28 stimulation seems to have a special significance in the predisposition for HPV infection." (PMID 35651609, 2022). "Therefore, further investigations on CD8+ TEMRA are encouraged as the loss of CD28 expression might lead to impaired T cell functions and hence decreased in host protection during COVID‐19 and other viral infections." (PMID 34861051, 2022). "By contrast, CTLA4 is another ligand for CD80/CD86 which presents even a higher avidity than CD28, acting as a critical inhibitor of T-cell activation and proliferation in several viral infections." (PMID 36713151, 2022). "In peripheral blood, CD4+ T cells with low CD27, CD28, and CCR7 expression associate with viral infections and display cytotoxic functions." (PMID 30389931, 2018). "The size of the latently infected TCM cell population was estimated by the fraction of cells that expressed HIV in response to CD3/CD28 stimulation and ranged from approximately 20% to 50%, depending on the viral infection and donor." (PMID 29170390, 2017). "During the primary viral infection, Cd28−/− or Ox40−/− mice developed a small number of memory CD8+ T cells compared to Wt mice." (PMID 26791245, 2016). "A number of animal models for viral infections have demonstrated that costimulatory molecules of both the CD28 and the TNFR family members aid in the generation and/or maintenance of virus-specific memory CD8+ T cells." (PMID 26791245, 2016). "As the context of a viral infection determines the dependence on CD28/B7-mediated costimulation for CD8+ T cell expansion, we compared the overall composition of inflammatory mediators in LCMV and MCMV infection." (PMID 26263500, 2015). "Human CD8+ effector memory T cells observed in various virus infections have been subdivided further into “early”, “intermediate” and “late” based on differential expression of CD28 and CD27." (PMID 21124875, 2010). "The C1.7+/CD28+ subsets of CD8+ T cells is associated with higher cytotoxic activity and interferon-gamma production, and this subset is thought to control viral infections by mediating cytolytic activity against viral infected cells." (PMID 17521440, 2007). "Although both CD80 and CD86 provide costimulatory signals through CD28, it remains unclear whether they can fully compensate for each other’s functions during viral infections." (PMID 41280933, 2025). "CD28 engagement provides essential co-stimulatory signals that enhance T cell activation and effector functions, leading to an effective immune response against viral infections." (PMID 38357647, 2024). "CD28, a cell surface receptor, has been recognized as a significant marker of immune activation due to its vital role in promoting the proliferation and maintenance of T helper cells during viral infections." (PMID 38357647, 2024). "In addition, Cd28 is necessary for humoral responses to viral infection, vaccination, and in allergy models." (PMID 35885926, 2022).
viral infection (continued). "Taken together, these results indicated that infection with both HCVcc and HCVpp increased IgM production and by downregulation of B7.2, attenuated CD28-mediated IgM production; thus virus infection enhanced the differentiation of memory B cells into IgM-secreting plasmablasts." (PMID 28067225, 2017). "Collectively, our data suggest that an interplay between viral infection and genotype might be important for CD28 expression." (PMID 28794437, 2017). "Next, we determined if an over-expression of survivin in Cd28−/− or Ox40−/− CD8+ T cells could reverse their defective generation of memory T cells during viral infection." (PMID 26791245, 2016). "Recall of memory responses to persistent viral infections is dependent on CD28." (PMID 24516382, 2014). "We show that continued CD28 expression is important for effector CD4+ T cells following infection; maintained CD28 is required for the expansion of T helper type 1 cells, and for the differentiation and maintenance of T follicular helper cells during viral infection." (PMID 25347065, 2014). "To determine if maintained CD28 expression is important for the immune response to bacterial infection, and not only viral infection, we infected Cd28flox/floxOx40cre/+ mice with Citrobacter rodentium, an enteric mucosal murine pathogen that elicits a robust humoral and cellular immune response." (PMID 25347065, 2014). "The data indicate that CD28-mediated expansion of Tregs in the periphery during the persistent phase of the viral infection induced a transient release of the viral infection from immunological control resulting in a dramatic increase of virus replication and spread in the CNS." (PMID 22448284, 2012). "However, PD-L1 and B7/CD28 expression in these viral infection models and tumor models, which may be relevant for the therapeutic efficacy, were unclear." (PMID 29255458, 2017). "In the case of viral infections, an increased abundance of CD4+CD27-CD28+ cells may be an early indicator of the prioritized loss of CD27 in CD4+ T cells, with the eventual loss of the CD28 antigen as cells progress to a differentiated state, in contrast with CD8+ T cells." (PMID 38502582, 2024). "CD86, a critical costimulatory molecule and ligand for CD28 and CTLA-4, is upregulated on monocytes and DCs upon virus infection in vitro and in vivo." (PMID 36752598, 2023). "MAT CD8+ T cell responses were depressed both in vivo following sublethal viral infection and in vitro following TCR/CD28 stimulation." (PMID 28337207, 2017). "In summary, we provide evidence that the transcriptional regulation of c-Myc, together with Nfkb1 from CD28 or TNF family members, controls the development of memory CD8+ T cells during viral infection." (PMID 26791245, 2016). "Collectively, these results demonstrated that the regulation of c-Myc from costimulatory signals affects the expansion (CD28) and the contraction (OX40) of virus-specific memory CD8+ T cells during the primary viral infection." (PMID 26791245, 2016). "C-Myc expression was dramatically reduced in Cd28−/− or Ox40−/− memory CD8+ T cells, and c-Myc over-expression substantially reversed the defects in the development of T-cell memory following viral infection." (PMID 26791245, 2016). "CD28 co-stimulation can affect the optimal development of secondary responses, proliferation of memory CD4+ and CD8+ T-cells and clearance of viral infections." (PMID 22253710, 2012). "The progression of CD8+ T cell differentiation from CD27+CD28+ to CD27+CD28- and lastly CD27-CD28- has been observed repeatedly in human viral infections (Influenza, HCV, EBV, HIV, and CMV), confirmed with telomere length studies and in in vitro assays using human cells." (PMID 29176779, 2017). "To show that the expression of c-Myc or CA-IKKβ alone could reverse defective development of memory CD8+ T cells in Cd28−/− or Ox40−/− T cells, we assessed the frequencies of transferred CD8+ T cells during viral infection." (PMID 26791245, 2016).
viral infection (continued). "In contrast, the absence of CD28 costimulation during recall of memory responses to T. gondii infection and viral infections inhibited the development of protective memory responses." (PMID 24516382, 2014). "Our data thus do not support a universal role for CD8+ CD28+ T cells in control of chronic viral infection." (PMID 16859558, 2006). "Thus, 'humanized' PYAP mice reveal key roles for CD28 signaling strength in CD8 activation, accelerating exhaustion during antigen persistence, while promoting and sustaining Tpex during acute and chronic viral infection." (PMID 40161835, 2025). "Therefore, the immune system obviously has more problems to deal with virus infections when CD28 is suddenly lost without the possibility that adaptive mechanisms take place." (PMID 37090733, 2023). "Furthermore, the percent of CD4+ and/or CD8+ T cells lacking CD28 expression also correlated with miRNAs regulating clusters of genes known to be involved in viral infection." (PMID 27853459, 2016). "Moreover, over-expression of survivin with bcl-xL, a downstream molecule of NF-κB and intracellular target of costimulation that controls survival, in Cd28−/− or Ox40−/− CD8+ T cells, reversed the defects in the generation of memory T cells in response to viral infection." (PMID 26791245, 2016). "The defective proliferation and survival of Cd28−/− or Ox40−/− CD8+ T cells may be due to lack of critical factors which result in reduced generation of memory CD8+ T cells during viral infection." (PMID 26791245, 2016). "The PBj-wt virus infection model displays exaggerated features in respect to mitogenic signaling and kinase activation most likely due to the presence of the ITAM motif in PBj-Nef, which may result in CD3/CD28 co-stimulus independency." (PMID 21366921, 2011). "The sorted cells were subsequently cultured with an integrase inhibitor, preventing new rounds of virus infection, and treated with 100 U/mL of IFN (α, β, ε, ω, λ1 or λ3) in the presence or absence of anti-CD3/CD28+IL-7+IL-2." (PMID 32109259, 2020).